TNF (tumor necrosis factor)
Diseases named in the same sentence as TNF in open-access papers (continued):
Sharing a sentence is not in itself a finding about the gene and the disease.
lupus (continued). "In lupus mice, B. pinnatum reduced T cell activation and B cell maturation, decreased production of TNF-α and improved histopathological nephritis markers." (PMID 38130407, 2023). "Up-DEGs were enriched in Systemic lupus erythematosus, Alcoholism, Neutrophil extracellular trap formation, Transcriptional misregulation in cancer, TNF signaling pathway, and IL-17 signaling pathway in KEGG." (PMID 37088824, 2023). "For example, in systemic lupus erythematosus, biomarkers such as IL-18 and TNFα are preferred over CRP for disease monitoring." (PMID 37476185, 2023). "The DEGs in GV_III were predominantly associated with the structural constituent of chromatin, signaling receptor binding, extracellular space, systemic lupus erythematosus, the TNF signaling pathway, and the relaxin signaling pathway." (PMID 37958486, 2023). "The authors found that TNF-α was dominantly expressed and significantly correlated with a glomerular damage score in lupus-prone mice." (PMID 37373215, 2023). "In parallel, it has been estimated that 25% of adolescents with lupus are obese, demonstrating poorer sleep quality, worse physical, social and emotional functioning, and higher serum tumor necrosis factor-α (TNF-α) levels, while experiencing more pain." (PMID 37189946, 2023). "Protein-digestion-and-absorption-, systemic-lupus-erythematosus-, and TNF-signaling-pathway-related gene sets were downregulated in response to acute AE combined with PI." (PMID 37571423, 2023). "Consistent with these previous findings, we found that levels of phosphorylated ERK and TNFα and IL-1β protein in lupus mice were higher than those in normal controls." (PMID 37440542, 2023). "Vitamin E has antioxidant and anti-inflammatory effects and, because of its anti-inflammatory effect, seeks to reduce IL-2, IL-4, and TNF-α, which can be effective in lupus." (PMID 37511964, 2023). "Increased levels of miR-146a are related to the inhibition of pro-inflammatory cytokine production (IL-6, TNF-α, and IL-1β) and the expression of inflammatory mediators, leading to the survival of lupus-prone mice." (PMID 37372034, 2023). "An in vitro study on pristane-induced lupus BALB/c mice found that the use of S. baicalensis downregulated the production of proinflammatory cytokines such as TNF-α, IL-6, IL-10, and IFN-γ." (PMID 37511964, 2023). "Using lupus-prone model mice, the (NZBxNZW)F1 system, the physiological functions of TNF-α have been investigated." (PMID 35884790, 2022). "HSP90AA1 affects the patient’s reaction with systemic lupus erythematosus to glucocorticoids and the lipopolysaccharide-induced inflammatory response, including tumor necrosis factor secretion by monocytes, according to previously published findings." (PMID 35330393, 2022). "Even more puzzling has been the development of autoantibodies and lupus in patients treated with TNF inhibitors despite the robust inhibitory effect of these drugs on the GC, a site where pathogenic autoantibodies are often generated." (PMID 35104241, 2022). "The marginal zone repertoire in 3H9 Sle1 and 3H9 Sle1 TNF–/– mice was highly restricted, with a high frequency of Vk12-46 light chains as we have previously reported in other lupus strains." (PMID 35104241, 2022). "In FcgRIIb-/- lupus mice, LPS from gut leakage in synergy with BG induces prominent M1 pro-inflammatory macrophages partly through the induction of TNF-α and IL-6." (PMID 35897790, 2022). "Not surprisingly, studies in patients and lupus mice also exhibit an increasing baseline of TNF-α and IL-6 compared to healthy volunteers, which correlates with lupus disease severity." (PMID 35897790, 2022). "The vast majority of patients achieve complete or partial resolution of their lupus-like reactions upon the withdrawal of TNF-α inhibitors, with a subset requiring ongoing lupus-specific therapy." (PMID 35884790, 2022).
lupus (continued). "Decreased MHCII, CD40, TNF-α, C2, and C7 in the systemic lupus erythematosus signaling pathway further downregulate MAC expression and reduces tissue damage and inflammatory response." (PMID 36245510, 2022). "John’s wort) proved effective in significantly reducing the serum level of IFN-g, IL-17A, IL-1b, TNF-a, and IL-6 in lupus-prone mice." (PMID 35431950, 2022). "Artemisinin, the main component of Qinghao, can inhibit the production of serum anti-ds-DNA in lupus-like mice and has an inhibitory effect on the secretion of TNF-α in serum." (PMID 35571092, 2022). "IL-2 and IL-10 depletion and a shift to the Th-1 pathway in the innate response are the correlated mechanism for tumor necrosis factor-alpha inhibitor-induced systemic lupus erythematosus." (PMID 35733860, 2022). "The objectives of the study were to investigate the mechanisms of tumor necrosis factor-alpha inhibitor-induced systemic lupus erythematosus." (PMID 35733860, 2022). "Deletion of either miR-183C or miR-182 alone had no changes on the serum levels of IFNγ, IL-6, or other selected lupus-related cytokines, such as TNFα, IL-10, and IL-17." (PMID 35873462, 2022). "In patients with CD and UC, the rate of anti-TNF induced lupus is 0.19–5.7% for infliximab and 0.1–0.6% for adalimumab." (PMID 33802483, 2021). "Pathway enrichment analysis of these hub genes suggested involvement in pathway regulation, including Systemic lupus erythematosus, Alcoholism, Viral carcinogenesis, Osteoclast differentiation, Adipocytokine signaling pathway, and TNF signaling pathway." (PMID 33868359, 2021). "PDC and NK cells in the presence of interferon inducers, such as RNA-containing immune complexes, produce tumor necrosis factor -α (TNF-α) and IL-6, among other pro-inflammatory cytokines, as in systemic lupus erythematosus." (PMID 34827548, 2021). "The role of cytokines in lupus is supported by reports of elevated Tumor necrosis factor (TNF)-α and Interferon (IFN)-γ in SLE patients." (PMID 35069220, 2021). "We report a case of an 18-year-old Hispanic male with CD who acquired anti-TNF-α-induced lupus after infliximab therapy presenting with pleural effusion and pericarditis." (PMID 34336341, 2021). "In epidermal cells and patients with systemic lupus erythematosus, TNF-α is proinflammatory and TGF-β is anti-inflammatory." (PMID 35069596, 2021). "Patients with SLE reported elevated serum concentration for TNF‐α,16 and TNF‐α signalling contributed to lupus development in lupus‐prone mice." (PMID 33079487, 2020). "It is interesting to note that monocytes from systemic lupus erythematosus have defects in adhesion and produce elevated levels of IL-6, TNF-a, and IL-10 than healthy monocytes." (PMID 32645059, 2020). "Studies have unveiled the promoted levels of TNF-α and C-C Motif Chemokine Ligand 5 (CCL5) mRNA provoked by TLR4 and TLR7 in spleen macrophages of lupus-susceptible mice." (PMID 32760274, 2020). "Immunohistochemistry staining demonstrates that a large amount of TNF is expressed in arthritic joints in lupus MRL/lpr mice." (PMID 32994999, 2020). "For instance, resveratrol ameliorated the disease symptoms by reducing B and Th1 cells in lupus-prone mice, decreasing inflammatory cytokines (TNF-α and IL-1β) in RA-induced rats and inhibiting cell adhesion molecules (ICAM and VCAM) in db/db mice." (PMID 33333788, 2020). "Normalizing ERK1/2 in lupus‐prone mice reduced expression of IL‐1β, TNF‐α and IL‐6 and relieved development of lupus." (PMID 33079487, 2020). "In SLE patients and lupus-prone mice models, high levels of proinflammatory cytokines such as TNF-α, IFN-γ and IL-6 are present during active lupus." (PMID 32421738, 2020). "Other adverse effects of TNF-α inhibitors include injection site reactions, upper respiratory tract infections, drug-induced lupus, abnormal liver function tests, and palmoplantar pustulosis, which were noted in US systemic reviews in 2018 and 2019." (PMID 32512854, 2020).
lupus (continued). "It has been shown that recombinant TNF‐alpha induces a significant delay in the development of the nephritis in lupus mice." (PMID 32994999, 2020). "This is supported by the observation of increased expression of the proinflammatory cytokines IFN-α and TNF-α in the whole blood of female African American lupus patients compared with female European American patients." (PMID 33108347, 2020). "The results showed that plasma levels of TNF‐α, IL‐1β, IL‐6 and IL‐23 were significantly up‐regulated in pristane‐induced lupus mice compared with those in the control group." (PMID 33079487, 2020). "TNF-α inhibitors are currently used to treat a variety of immune-related disorders including sarcoidosis, lupus, and plaque psoriasis." (PMID 33324666, 2020). "Further, in addition to IFNα, pristane induces production of numerous NFκB-induced cytokines, including IL-6, IL-1b, and TNFα, which contribute to other manifestations of lupus." (PMID 33101313, 2020). "Though not all changes were statistically significant, similar observations were made for TNF-α, IL-1α, IL-6, and IL-18, which are known for their roles in inflammation and lupus development." (PMID 32413078, 2020). "Renal dysfunction is often a consequence of the autoimmune disease systemic lupus erythematosus (SLE), and ADAM17 substrates TNFα and heparin-binding EGF (HB-EGF) have been implicated as important mediators of this condition called lupus nephritis (LN)." (PMID 30890028, 2019). "Reduced lupus disease manifestations were seen, as well, in BXSB/MpJ and MRL-lpr lupus-prone mice, together with a reduced expression of the proinflammatory cytokines IL-6, IL-12, and TNF-α." (PMID 31137916, 2019). "The phenolic fraction of extra virgin olive oil has anti-inflammatory and immunomodulatory properties that associated with a reduced production of pro-inflammatory TNF-α, IL-6, IL-1β, and IFN-γ in 38 lupus patients’ peripheral blood mononuclear cells (PBMCs)." (PMID 31137916, 2019). "Since TNF has dualistic suppressive and promotive effects on lupus condition, timing and duration of TNF exposure or inhibition seem to be critical." (PMID 31052273, 2019). "In the current study, we inhibited Syk downstream of FcγR, which decreased the inflammation induced by lupus IgG, and decreased NF-κB signaling and TNF-α secretion induced by lupus IgG in macrophages." (PMID 32082297, 2019). "Lupus IgG promotes inflammation though macrophage-mediated secretion of TNF-α and further promotes GC formation." (PMID 32082297, 2019). "The results demonstrated that macrophage and pro-inflammatory TNF-α are required for the development of hepatic inflammation induced by lupus IgG." (PMID 29988500, 2018). "Another histone modification in lupus patients is H3 and H4 acetylation, which is correlated with TNF-α locus and causes TNF-α hyper-expression in monocytes of SLE patients." (PMID 29803202, 2018). "It is worth noting that anti-TNF therapy often results in psoriatic and lupus-like symptoms in patients being treated for other conditions; this suggests a direct correlation between TNF and immune suppression." (PMID 29619032, 2018). "Though combinations of hCG and ODN1826 resulted in greater increases in TNF-α secretion than elicited by individual moieties in both healthy and lupus-prone mice, a bias toward greater increases in the latter was apparent in this case as well." (PMID 30574119, 2018). "Proinflammatory cytokines such as TNF-α and type I interferons (IFN) are pathogenic signatures of systemic lupus erythematosus, and plasmacytoid dendritic cells (pDCs) play a major role by predominantly producing IFN-α." (PMID 28367002, 2017). "For example, DHA prevents tumor necrosis factor-alpha (TNF-α)-induced senescence and dysfunction in endothelial cells, while concentrated fish oil extends the lifespan of lupus-prone short-lived (NZB×NZW)F1 mice." (PMID 28038469, 2017).
lupus (continued). "The increased levels of TNFα in the serum of SLE patients are consistent with the low expression of P-Selectin that we found in the skin of lupus patients." (PMID 28150814, 2017). "As the use of anti-TNF-α therapy has been increasing, various paradoxical inflammations such as cutaneous vasculitis, drug induced lupus and sarcoidosis have been reported in recent years." (PMID 26864464, 2016). "Impaired HRV, particularly the LF/HF ratio, is associated with lupus disease activity and several cytokines related to IFN type II and TNF pathways." (PMID 27590046, 2016). "This can be explained either by an “unmasking” effect in predisposed patients, or a drug-induced effect, a clinical entity referred as anti-TNF induced lupus, ATIL." (PMID 27260006, 2016). "Thalidomide, currently used in multiple myeloma treatment but also tried in lupus and RA, is a potent TNF-α antagonist and angiogenesis inhibitor." (PMID 27211044, 2016). "BMMSCs derived from patients with systemic lupus erythematosus, which have impaired bone forming potential, express enhanced phosphorylation of NF-κB under accelerated TNF-α signaling." (PMID 26775677, 2016). "Recently, it has been reported that anti-TNF-α therapy induces so-called paradoxical inflammations, including anti-nuclear antibody production, drug induced lupus, vasculitis and sarcoid-like granulomatous disease." (PMID 26864464, 2016). "Abnormal production of inflammatory cytokines such as IFNγ, IL-1β, IL-6, and TNFα is a key characteristic of lupus." (PMID 27070142, 2016). "Increased production of tumor necrosis factor α, interleukin (IL)-1, IL-6, and other pro-inflammatory cytokines has been reported in patients with SSc and systemic lupus erythematosus who have calcinosis." (PMID 26134593, 2015). "Lupus patients, particularly African Americans, had significantly higher levels of IL-6 (p = 0.0001) and TNF-α (p = 0.042)." (PMID 26583155, 2015). "After multivariate analysis, systemic lupus erythematosus, use of sulfasalazine or a tumor necrosis factor inhibitor, and a manual ELISA system remained significantly independent predictors of indeterminate results." (PMID 25961292, 2015). "En effet, le lupus est une maladie inflammatoire chronique qui s'accompagne d'une hyperproduction de cytokines pro-inflammatoires telles que le TNF alpha et l'interleukine 6 dont les taux élevés sont corrélés à la présence de calcifications coronaires." (PMID 27022427, 2015). "The most frequent adverse events related to anti-TNF-α therapies are infectious diseases, malignancies, demyelinating diseases, and drug-induced lupus." (PMID 24707429, 2014). "Preliminary studies on lupus prone mice models have documented high concentrations of TNF-α in both sera and renal tissue and they were correlated with severity of kidney disease." (PMID 25548434, 2014). "Scientists have shown that Quercetin (an important antioxidant in calligonum extract) can alter gene expression of TNFα in lupus patients." (PMID 25114667, 2014). "The emergence of autoimmunity manifested as positive ANA, anti-DNA antibodies, and drug-induced lupus during anti TNF-α therapy has been widely documented." (PMID 24600322, 2014). "In the contemporary era of biologic therapy, anti-TNF has been increasingly used in the treatment of inflammatory arthritis, but cases of anti-TNF-induced lupus have been reported." (PMID 25216337, 2014). "These authors reported that OPN gene polymorphism induces enhanced expression of immunoglobulins: IgG3, Ig2a and IgM and cytokines: IFN-γ, TNF-α, IL-1β which play an important role in lupus mice models and in human SLE." (PMID 24917428, 2014). "TNF is highly over expressed in both sera and renal tissue of the lupus mice and the levels of TNF is correlated with the degree of inflammatory organ disease." (PMID 23702100, 2013). "Neurological symptoms onset in patients on TNFα blockers should lead to exclude infections, induced lupus but also paradoxical neurosarcoidosis." (PMID 24373564, 2013).
lupus (continued). "In patients with active lupus, increased serum levels of tumor necrosis factor (TNF) and oxidized low-density lipoprotein (LDL) were demonstrated." (PMID 22477520, 2012). "We then extended our studies to assess the effect of NCS 613 on LPS-induced TNFα secretion by PBLs from lupus patients." (PMID 22247763, 2012). "In patients with systemic lupus erythematosus, high serum levels of TNFα correlating with disease activity have been described, and its role in the development of lupus nephritis is accepted." (PMID 23079185, 2012). "TNFα protein production by PBMCs is greater in DLE patients than in patients with other cutaneous forms of lupus and DM or in controls." (PMID 22217359, 2012). "The MHC genes including TNFα, HSP70, and class II genes have been associated with systemic lupus erythematosus." (PMID 22761632, 2012). "In the case of TNF-α, almost 90% of the lupus monocyes secreted TNF-α above the normal range; the magnitude of this increase varied widely among the patients." (PMID 21423726, 2011). "In this report, we provide the first evidence that human lupus monocytes have a unique pattern of cytokine secretion in response to apoptotic cells, which is paradoxically characterized by high TNF-α and low TGF-β production." (PMID 21423726, 2011). "It is noteworthy that the range of TGF-β and TNF-α secretion by lupus monocytes was quite heterogeneous among the patients." (PMID 21423726, 2011). "Paradoxically, lupus autoantibodies facilitate apoptotic cell clearance and interestingly, trigger TNF-α release by macrophages isolated from healthy donors." (PMID 21423726, 2011). "We further showed that nucleic acids from apoptotic cells play important role in the induction of TNF-α by lupus monocytes." (PMID 21423726, 2011). "On the other hand, other studies showed high levels of TNF-alpha in mice with lupus and reported acceleration of renal injury after its administration." (PMID 27713252, 2010). "Anti-nuclear antibodies (ANAs) develop in 30 to 60% of the patients given anti-TNFα regimens and, occasionally, clinical lupus develops during the course of therapy." (PMID 19563672, 2009). "Changes of this magnitude are biologically significant, because lupus patients have elevated serum TNF-α and IL-1β concentrations of a similar magnitude compared with controls." (PMID 20049214, 2009). "Both lupus and control moDCs expressed surface MR, which significantly downregulated upon stimulation/maturation with LPS and TNFα (P = 0.03 for lupus DCs, P = 0.007 for control)." (PMID 18811944, 2008). "CD40L treatment of bone-marrow-derived DCs from lupus-prone B6.TC mice induced higher production of IL-6, IL-10, and TNF-α than in B6 mice." (PMID 18718031, 2008). "Monoclonal antibody against TNF alpha blocked the lymphocytopenic features characteristic of acute graft versus host disease and induced a lupus-like chronic graft versus host disease phenotype (lymphoproliferation and autoantibody production)." (PMID 15899041, 2005). "We hope that the national observatories and registers that have been settled in various countries around the world will precisely and prospectively answer the question of anti-TNF-induced lupus." (PMID 15899041, 2005). "The development of drug-induced lupus remains a matter of concern in patients treated with anti-tumour necrosis factor (TNF) alpha." (PMID 15899041, 2005). "In conclusion, we collected 22 cases of 'anti-TNF alpha-induced lupus' based on the ACR lupus criteria in a retrospective national survey, allowing us to better define the clinical aspects of these manifestations." (PMID 15899041, 2005). "Other dermatological conditions that occurred during or after TNF-α-blocking therapy included, among others, dermatomyositis, drug-induced systemic lupus erythematosus, and lymphomatoid papulosis-like eruption." (PMID 15899052, 2005).